CASR (calcium sensing receptor)
Diseases named in the same sentence as CASR in open-access papers (continued):
Sharing a sentence is not in itself a finding about the gene and the disease.
Hypercalcemia (continued). "Before age 8, almost all cases of PTH-dependent hypercalcemia are caused by familial hypocalciuric hypercalcemia (mostly from mutation in CASR, AP2S1, or GNA11) or by neonatal severe primary hyperparathyroidism, both of which have near 100% penetrance for hypercalcemia already in the neonate." (PMID 30065698, 2018). "Hypercalcemia-associated AP2σ mutations reduced CaSR signaling via Gαq/11 and Gαi/o pathways." (PMID 29420171, 2018). "NSHPT is a rare life-threatening disease characterized by marked hypercalcemia, diffuse parathyroid hyperplasia and skeletal demineralization, due to the biallelic inactivation (homozygous or compound heterozygous mutations) of the CaSR gene." (PMID 30376845, 2018). "However, this filter also had the most significant association of the entire study (CASR and hypercalcemia), as well as the most significant associations for ICD-9 based diagnoses." (PMID 29545597, 2018). "Hypercalcemia in patients with advanced and/or metastatic disease has been reported to be strongly associated with poor prognosis while inactivating mutations of the CaSR in exon 7 promoted the development of hypercalcemia in a xenograft mouse model of human squamous cell lung carcinoma." (PMID 28764683, 2017). "Severe neonatal hypercalcaemia is also reported to be associated with heterozygous loss-of-function CaSR mutations, and these findings indicate that NSHPT may be due to factors other than mutant gene dosage." (PMID 27647839, 2016). "In the present study, we showed that the Val258ArgfsTer47 mutation in the CaSR gene identified in a young patient with hypercalcemia and her father resulted in a significant reduction of CaSR sensitization to extracellular Ca2+ leading to typical features of FHH." (PMID 27087013, 2016). "An infant with a maternally inherited mutated allele will have a more benign clinical picture than an infant with a paternally inherited mutated allele because the resulting mild maternal hypercalcemia helps to activate the mutated fetal CaSR and inhibit expression PTH secretion." (PMID 22620673, 2012). "To explore the relationship between the variant sites and hypercalcemia, we used bioinformatics software to conduct conservation analysis of homologous species and protein function prediction analysis, further revealing the protein structural changes caused by the missense variants of CaSR." (PMID 40417236, 2025). "Because hypercalcemia is a well-known risk factor for pancreatitis, and given the tight bond between the CaSR and serum calcium homeostasis, it was speculated that CaSR mutations or SNPs could be linked to pancreas inflammation." (PMID 36467702, 2022). "Due to a decrease in CaSR signal transduction, it typically exhibits hypercalcemia, hypocalciuria, hypermagnesemia, and hypophosphatemia." (PMID 39949382, 2025). "Cinacalcet hydrochloride (CIN) is a calcium-sensing receptor agonist used to treat hypercalcemia in the parathyroid." (PMID 40234287, 2025). "Kidney stones, parathyroid hyperplasia, mild hypercalcemia, and hypercalciuria have been described in a kindred with the FHH-associated CaSR loss-of-function mutation F881L." (PMID 40372791, 2025). "Elevated serum calcium concentrations or the administration of exogenous calcimimetic agents can suppress calcium absorption via TRPV6 by activating the calcium-sensing receptor (CaSR) in intestinal epithelial cells, thus mitigating the onset of hypercalcemia." (PMID 40417213, 2025). "NSHPT is a rare disorder consisting of hyperparathyroidism and marked hypercalcemia because of inactivation of the CASR gene." (PMID 39129820, 2024). "In breast cancer, the CaSR acts as a stimulator of tumorigenesis by promoting the secretion of PTHrP, which is responsible for hypercalcemia and cancer progression." (PMID 38920679, 2024). "It mimics the action of calcium by allosteric activation of the calcium-sensing receptor and is used to treat hypercalcaemia due to hyperparathyroidism." (PMID 36835602, 2023).
Hypercalcemia (continued). "And hypercalcemia activates the calcium-sensing receptor (CaSR) in the thick ascending limb of Henle and medullary collecting duct which cause hypercalciuria, natriuresis and diuresis." (PMID 35187010, 2022). "Under physiological conditions, several organ systems are affected by activation of the CaSR due to hypercalcemia." (PMID 35566721, 2022). "During the period after the cinacalcet therapy had been discontinued, this patient showed slight hypercalcemia, indicating that CaSR autoantibodies continued to be produced." (PMID 36099030, 2022). "Heterozygous loss-of-function mutation of the calcium sensing-receptor (CaSR), causes familial hypocalciuric hypercalcemia type 1 (FHH1), a typically benign condition characterized by mild hypercalcemia." (PMID 35857775, 2022). "In the kidney, CaSR prevents the reabsorption of divalent cations in the thick ascending limb of the loop of Henle, triggers the inhibitory actions of hypercalcemia on the urinary-concentrating mechanism, and subsequently prevents kidney stone formation." (PMID 36088585, 2022). "Stimulation of the CaSR by hypercalcemia leads to inhibition of osteoclastic resorption and increased osteoblastic activity." (PMID 35566721, 2022). "Monogenic causes of hypercalcaemia are broadly divided into PHPT syndromes, those in which PHPT occurs as an isolated endocrinopathy, disorders associated with impaired CaSR signaling, and conditions associated with abnormal vitamin D metabolism." (PMID 34935164, 2022). "Cinacalcet, a calcium-sensing receptor (CaSR) allosteric agonist is used to control hyperparathyroidism and hypercalcemia in a number of clinical scenarios." (PMID 36601343, 2022). "However, in the last few years, polymorphisms of the CaSR became the target of numerous oncological investigations as they may contribute to the development of cancer-induced hypercalcemia and consequently influence the clinical outcome of different malignant diseases." (PMID 33528764, 2021). "By the 10th week of gestation PTH is synthesised from fetal parathyroid glands, but circulating concentrations are kept low during fetal life due to relative hypercalcaemia dictated by the CaSR." (PMID 33614549, 2021). "Based on this patient’s strong family history of hypercalcaemia and the pattern of inheritance of an autosomal dominance CASR gene, it is likely that both her maternal grandmother and mother carried the defected CASR gene which was passed on to the patient." (PMID 31797261, 2020). "The same failures also demoted CaSR NAMs from the drugs potentially beneficial in humans even because of the modest hypercalcemia (hyperparathyroidism) they induced." (PMID 31719824, 2019). "Cinacalcet, a calcimimetic, is an allosteric modulator of the CaSR that efficiently decreases hypercalcemia in PTH‐dependent disease." (PMID 31044184, 2019). "Considering the early onset, life-threatening hypercalcemia and the biochemical findings in the patient, genetic studies of CASR gene were performed revealing NSHPT secondary to a CaSR gene mutation." (PMID 30376845, 2018). "CaSR agonist cinacalcet was effectively used to lower the blood calcium level in BrCa patients with hypercalcemia." (PMID 30151009, 2018). "Hypercalcaemia is associated with increased acid discharge, since the secretion of gastrin and calcitonin is stimulated by the hypercalcaemia via the intermediary of the CaSR present in the gastrin-secreting cells." (PMID 28122587, 2017). "Hypercalcemia-related symptoms can be controlled by cinacalcet HCl, a potent agonist of the calcium sensing receptor (CASR)." (PMID 28157158, 2017). "Here we demonstrate that fetal hypercalcemia, acting through the CaSR, promotes human fetal lung growth and expansion via CFTR." (PMID 26911344, 2016).
Hypercalcemia (continued). "Colloton and coworkers investigated the ability of cinacalcet, an allosteric modulator of CaSR, to attenuate hypercalcemia in mice bearing H-500 cells and indeed demonstrated that cinacalcet effectively reduced tumor-mediated hypercalcemia." (PMID 27625611, 2016). "Investigators studying CASR knockout mouse models demonstrated that the CASR also defends against hypercalcemia by increasing calcium excretion by the kidney, independent of its role in the parathyroid glands." (PMID 27803672, 2016). "Together, these observations suggest that physiological fetal hypercalcemia, acting on the CaSR, promotes human fetal lung development via cAMP-dependent opening of CFTR." (PMID 26911344, 2016). "On the basis of our current findings, we suggest that mutations, which affect expression and/or function of CFTR, would lead to a reduction of increases in fluid secretion induced by fetal hypercalcemia via CaSR activation." (PMID 26911344, 2016). "Stimulation of PTHrP release initiates a vicious circle of hypercalcemia maintained by CaSR expression in Leydig cell tumors, which suggests CaSR as a potential therapeutic target for CaSR antagonists." (PMID 27625611, 2016). "This is a case of a novel inactivating point mutation of CaSR gene that determines an atypical clinical presentation of FHH, characterized by hypercalcemia, hypercalciuria and inadequate normal PTH levels." (PMID 25292184, 2014). "Cinacalcet is a calcimimetic that acts on the calcium-sensing receptor of parathyroid cells, reducing parathyroid hormone and attenuating hypercalcemia." (PMID 24524553, 2014). "Previously we have shown that fetal hypercalcemia exerts an inhibitory brake on branching morphogenesis via the calcium-sensing receptor." (PMID 24282533, 2013). "Patients with neonatal severe hyperparathyroidism (NSHPT) are homozygous for the calcium-sensing receptor (CaR) mutation and have very high circulating PTH, abundant parathyroid hyperplasia, and severe life-threatening hypercalcemia." (PMID 21966280, 2011). "Newer evidence suggests that the CaSR plays a role independently of parathyroid hormone in the renal tubules to promote calcium secretion in the face of hypercalcemia." (PMID 21747852, 2011). "Because two of her children had hypercalcemia and hypocalciuria as well, we carried out DNA sequencing in the CaSR gene in the patient and three of her children." (PMID 21034470, 2010). "The investigation of this Irish family with hypercalcemia led to the diagnosis of FHH and to the identification of a novel mutation in the CaSR gene." (PMID 21034470, 2010). "Rare monogenic forms of hypo- or hypercalcemia have been described, including disorders involving the calcium-sensing receptor (CASR, locus 3q13) gene." (PMID 20661308, 2010). "We believe that the molecular diagnosis of FHH through DNA sequencing or DHPLC of the CaSR gene is clinically useful in the differential diagnosis of hypercalcemia in elderly patients with multiple comorbidities." (PMID 21034470, 2010). "The Epfn KO, MEM1 cKO, and PTH‐CyclinD1 TG mouse models are associated with hypercalcemia, while the CaSR, Cyp27b1, and VDR KO mouse models have a normal serum calcium level despite elevated PTH due to impaired calcium absorption in the kidneys and intestine." (PMID 40164571, 2025). "Furthermore, although less common in adolescence, biallelic CASR mutations are a recognized cause of neonatal severe hyperparathyroidism (NSHPT), a life-threatening disorder manifesting with severe hypercalcemia and bony deformities." (PMID 41210508, 2025). "From case reports, CaSR deficiency was not evident at birth in humans but presented very early in neonatal life with symptomatic hypercalcemia." (PMID 39796238, 2025). "Failure of the CaSR to recognize elevated serum calcium leads to unopposed PTH activity, causing skeletal demineralization, decreased renal calcium excretion, and severe hypercalcemia, which can be fatal." (PMID 39129820, 2024).
Hypercalcemia (continued). "Some patients with non-syndromic PHPT may have mutations of the MEN1 gene or the calcium-sensing receptor (CASR), whose loss of function mutations usually cause FHH1, a disorder associated with mild hypercalcemia and may follow a benign clinical course." (PMID 38038882, 2024). "In humans, mutations in the CaSR cause familial hypocalciuric hypercalcemia in heterozygotes and neonatal severe hyperparathyroidism in homozygotes, resulting in inappropriately normal or elevated PTH concentrations in the face of hypercalcemia." (PMID 38887540, 2024). "Furthermore, CaSR is intricately involved in the intracellular degradation of PTH during episodes of hypercalcemia." (PMID 38920679, 2024). "In hypercalcemia, a conformational change in CaSR (Calcium sensing receptor) indirectly leads to the recruitment of Gq1 and Gqa subunits of the G protein, changing signalling inside the cell by reducing cAMP levels and activating MAP kinases and phospholipases." (PMID 36651710, 2023). "In addition, hypermagnesemia and hypercalcemia inhibit the reabsorption of Mg in the loop of Henle by stimulating the calcium-sensing receptor (CaSR)." (PMID 37049550, 2023). "In a recent study of individuals being evaluated for hypercalcemia, 6.1% of patients had rare CASR variants, 47% of which were not previously reported." (PMID 32386559, 2020). "The murine knock-out (KO) model of the CaSR (CaSR-/-), which is a model of human neonatal severe hyperparathyroidism, displays serious hypercalcemia, hypophosphatemia, and increased serum PTH that contribute to bone abnormalities, delayed growth, and, finally, to premature death." (PMID 31336912, 2019). "Similarly, the calcium-sensing receptor agonist cinacalcet has been advocated to control extreme hypercalcemia in pregnancy." (PMID 31065618, 2019). "Moreover, the induction of a mild hypercalcemia by CaSR NAMs has been a bit too much stressed as “hyperparathyroidism” creating a prejudice against their use in humans." (PMID 31719824, 2019). "One female patient who exhibited mild hypercalcemia, low PTH (8.6 pg/mL), normal 25OHD, and hypocalciuria was found to carry a de novo heterozygote mutation of the CaSR gene (p.994delK (C.2981del AGA) and was diagnosed as a case of familial hypocalciuric hypercalcemia (FHH)." (PMID 28443817, 2017). "In summary, we have established a mouse model for FHH2 and have shown the in vivo efficacy of cinacalcet in reducing plasma calcium and PTH concentrations, thereby illustrating the potential utility of this CaSR allosteric modulator for the treatment of hypercalcemia in patients with FHH2." (PMID 29046478, 2017). "His son showed the same mutation in CaSR gene, but no clinical signs or hypercalcemia although serum ionized calcium levels were close to the upper limit of normal values (1.30 mmol/L: normal range: 1.12-1.31 mmol/L)." (PMID 25292184, 2014). "We have demonstrated previously that this relative fetal hypercalcemia is an important signal in the pseudoglandular lung, balancing branching morphogenesis with fluid secretion via developmentally regulated expression of the CaSR." (PMID 24282533, 2013). "Metabolic alkalosis enhances the sensitivity of the CaSR to hypercalcemia." (PMID 24288027, 2013). "This neonate with intrauterine fractures and demineralization, moderate hypercalcemia and hyperparathyroidism was found to have a novel inactivating missense mutation of the CaSR not detected in her mother." (PMID 22620673, 2012). "One might speculate, that administering a CaSR activating agent in a state of reduced CaSR expression due to hypercalcemia—which applies to pHPT—might be ineffective." (PMID 21461394, 2011). "In the kidneys, the CaSR decreases calcium reabsorption, increases calciuresis, and decreases the concentrating ability of the kidney when sensing hypercalcemia, through its effect on the thick ascending limb of the loop of Henle and on the medullary collecting ducts." (PMID 21034470, 2010).
Hypercalcemia (continued). "Familial hypocalciuric hypercalcemia is a rare autosomal dominant disorder characterized by asymptomatic and non-progressive hypercalcemia due to mutations of the calcium-sensing receptor gene." (PMID 21034470, 2010). "Moreover, genetic testing is crucial in distinguishing FHH from PHPT in cases with mild hypercalcemia and hypocalciuria, as patients with inactivating mutations in CASR, GNA11, or AP2S1 do not benefit from parathyroidectomy." (PMID 41210508, 2025). "Oral cinacalcet may be an efficacious therapy for malignancy-related hypercalcemia to elevate 1,25-dihydroxyvitamin D. Furthermore, it is hypothesized that this effect is primarily mediated by the interaction of cinacalcet with CaSR in the intestine, with lesser effects on the bones and kidneys." (PMID 40531748, 2025). "Additionally, CaSR is involved in the intracellular degradation of PTH during hypercalcemia." (PMID 38920679, 2024). "In a recent study investigating the CaSR in cats with CKD with and without concurrent hypercalcemia, an association was found between 1/12 CaSR single nucleotide polymorphisms (SNPs) and PTH concentration, but not iCa concentration; however, calcitonin concentration was not measured." (PMID 38887540, 2024). "However, whether the expression of exon 7 inactivating CASR mutants in TNBC cells also influence the development of hypercalcemia remains to be fully elucidated." (PMID 35355564, 2022). "Whether the development of secondary malignancies at these sites is exclusively mediated by cancer-induced hypercalcemia via CaSR signaling or includes other complications such as CaSR-mediated stimulation of inflammation and/or tumor immune suppression remains to be fully elucidated." (PMID 34357109, 2021). "The phenotype of the Trpc1–/– mice is consistent with that of FHH in humans, and the possibility that mutations in the TRPC1 gene may be a cause of hypercalcemia in some patients with FHH who did not have CASR, GNA11, or AP2S1 mutations was therefore explored." (PMID 32213715, 2020). "Notably, three CaSR PAMs, i.e. Evocalcet, Etelcalcitide, and Cinacalcet, have successfully reached the clinical use to mitigate primary and secondary hyperparathyroidism and tumor-elicited hypercalcemias." (PMID 31719824, 2019). "Thus, molecular screening for CASR mutations should be performed when FHH is considered in the differential diagnosis of hypercalcemia, especially in the absence of one or more cardinal features." (PMID 28443817, 2017). "Double global CaSR knockout mice are used because deletion of the CaSR gene alone results in early death from the toxic effects of unregulated release of parathyroid hormone (PTH) from parathyroid chief cells as well as from the pathological effects of the consequent hypercalcemia." (PMID 27458380, 2016). "Two of the three sons we investigated were hypercalcemic and did carry the same GCA→ GAA mutation in the CaSR gene as their mother, whereas the normocalcemic son did not, strongly suggesting that the mutation was the cause of the hypercalcemia and the diagnosis of FHH." (PMID 21034470, 2010). "HPHPT chief cell patterns show a marked CaSR decreased expression along with an increased CYP27B1/VDR expression, suggesting an appropriate autocrine/paracrine counterregulation to hypercalcemia/high PTH." (PMID 41907687, 2026). "As an allosteric activator of the calcium-sensing receptor, cinacalcet inhibits PTH release, as well as lowers serum calcium, making the drug ideal for patients with hyperparathyroidism and hypercalcemia." (PMID 38820324, 2024). "In FHH type 1, CASR hypoactivity leads to increased renal calcium reabsorption and increased PTH production, which can result in hypercalcemia with inappropriately normal or elevated PTH." (PMID 37810884, 2023).